TNF (tumor necrosis factor)
Diseases named in the same sentence as TNF in open-access papers (continued):
Sharing a sentence is not in itself a finding about the gene and the disease.
COVID-19 (continued). "Taken together, our results indicate that the serum from COVID-19 patients who did not survive induces oxidative stress, lipid peroxidation, and ferroptosis in human endothelial cells through a mechanism that depends on TNF-α." (PMID 36829885, 2023). "Similarly, serum IL-6, CXCL8, TNFα levels were increased in hospitalized COVID-19 patients (n = 1484) compared to non-infected by SARS-CoV-2 (n = 257) and serum levels of these pro-inflammatory mediators were positively correlated with mortality." (PMID 36941580, 2023). "Recent data suggest that pre-existing auto-immune disease is associated with increased severity of COVID-19, but IBD was not the most frequent auto-immune disease in the dataset and the same study showed a protective effect of anti-TNF therapy, which is the most frequently used in patients with IBD." (PMID 37701431, 2023). "Additionally, two of the three patients who did not achieve seroconversion after COVID-19 vaccination were under therapy with TNF-α inhibitors (n=1, infliximab monotherapy; n=1, infliximab plus MTX low-dose)." (PMID 37006279, 2023). "Furthermore, recently it was discovered that natural killer (NK) cells and CD8+ T cells of patients with COVID-19 have a higher expression of the NK cell inhibitory receptor, NKG2A, which is characterized by lower intracellular amounts of CD107, IFN-γ, IL-2, TNF-α, and granzyme B." (PMID 36679947, 2023). "Contrarily, patients with COVID-19 who were severely infected experienced an excessive release of cytokines and chemokines, such as interleukin (IL)-1, IL-2, IL-6, IL-7, IL-8, IL-10, granulocyte-colony stimulating factor (GCSF), and tumour necrosis factor-alpha (TNF-α)." (PMID 36679947, 2023). "In fact, a few studies reported a decrease in IL-1β and/or TNF-α but not IL-6, which explains why IL-6 could be the sole determinant of severity in COVID-19." (PMID 37106750, 2023). "Similarly, the plasma level of IL-2, IL-7, IL-10, and TNF-α increased in ICU COVID-19 patients compared to non-ICU COVID-19 patients." (PMID 38152668, 2023). "This study demonstrated that even in the presence of microvascular and endothelial dysfunction followed by mild COVID-19 as well as during persistently elevated levels of proinflammatory cytokines and parameters of endothelial activation, such as TNFα and sICAM-1, serum ADA1 is not increased." (PMID 37685949, 2023). "Studies have demonstrated that the correlation of TNF-α and IL-1 with critical COVID-19 cases, and the immunomodulation of TNF-α and IL-1 by MSCs observed in this study could be a potential treatment for reducing COVID-19 mortality." (PMID 36835154, 2023). "It was shown that targets of the drug combinations (including TNF, IL1B, IL10, and CCL2) (p=5.72×10−5) and, specifically, its individual drugs including EH (p = 0.00142), PR (p=4.37×10−4), and GR (p=5.81×10−5) are significantly overlapped with COVID-19-related genes obtained from the CTD database." (PMID 36611603, 2023). "The COVID-19 disease-specific findings are consistent with the effect of metformin in reducing tumor necrosis factor (TNF-α) levels in women, suggesting that metformin may protect against CCOVID-19 through TNF-α-mediated pathway." (PMID 37868953, 2023). "Moreover, most of these correlations were lost in critical COVID-19 patients except the negative correlation of IL-6 with leptin levels, and positive correlations found between IL-10 and TNFα and Resistin." (PMID 36509969, 2023). "Furthermore, the serum level of TNF-α was elevated in bacterial pneumonia and COVID-19 groups, although not statistically significant." (PMID 38585537, 2023). "MiRNAs that were downregulated in serum of COVID-19 patients mainly target genes promoting angiogenesis (e.g., VEGFA, ANGPT2, COL4A1, FGF2, ZEB1), apoptosis, autophagy, stress response (e.g., ATG12, ATG14, ATG2B, SOD2, TXNIP), and inflammation (e.g., CXCL9, CXCL10, IL1R1, TNF)." (PMID 36032130, 2022).
COVID-19 (continued). "However, serum TNF-α, IL-1β, IL-6, and blood-bacteria-free DNA were not different between healthy control and mild COVID-19 cases." (PMID 35406667, 2022). "Based on the finding of high IL-6 and TNF-alpha CSF/serum ratios and indices in the only SARS-CoV-2-IgG-AI-positive patient tested but not in any other patients, such studies should evaluate also IL-6 and TNF-alpha as supplementary markers of acute intrathecal inflammation in COVID-19." (PMID 35057809, 2022). "Based on the results of core signaling analyses and considering relative protein/gene expression levels as compared with normal nasopharyngeal tissues, we choose TNF, NFkB, and HIF1A as common biomarkers (drug targets) of infections pathogenesis in both COVID-19-associated ARDS and non-viral ARDS." (PMID 35409008, 2022). "Importantly, another study has shown that BBR (900 mg/day, for 14 days) also could significantly reverse the changes in IL-6, TNF-α and C-reactive protein (CRP) levels in patients with severe COVID-19 with diarrhoea." (PMID 36147356, 2022). "However, IL-6 and TNF-α, but not testosterone and inhibin B are connected to older age in COVID-19 patients." (PMID 36381078, 2022). "First, because of its retrospective nature, more detailed laboratory testing of immune cell inflammatory factors was lacking, such as T cell count, tumor necrosis factor, and various types of interleukins, to more accurately judge the degree of inflammatory response in COVID-19 patients." (PMID 35795627, 2022). "Therefore, this study aimed to investigate the serum testosterone, inhibin B, intrleukin-6 (IL-6) and tumor necrosis factor-alpha (TNF-a) levels in different age groups of Jordanian males with SARS-CoV2 infection and to evaluate the correlation of these markers in male patients with COVID-19." (PMID 36381078, 2022). "In particular, nonspecific immune responses at the onset of COVID-19, such as the production of cytokines like TNF-α and IL-6 from macrophages or IFN-γ from bystander T cells, and lymphopenia have been believed to be risk factors for severity and mortality of COVID-19." (PMID 36447262, 2022). "Furthermore, the extent of inflammatory cytokine in serum, such as IL-6 and TNF-α, as well as lymphopenia, especially with respect to CD8+ T cells, positively correlates and serves as a better predictor for severity and mortality in COVID-19." (PMID 35883618, 2022). "EGFR, interleukin 17 (IL-17), tumor necrosis factor (TNF), hypoxia inducible factor 1 (HIF-1), phosphoinositide 3-kinase/AKT serine/threonine kinase (PI3K/AKT) and Toll-like receptor signaling pathways were identified as the key anti-COVID-19/PF co-occurrence pathways." (PMID 35754492, 2022). "The pathogenesis of COVID-19 was mainly involved and regulation of multiple pathways such as NOD-like receptor signaling pathway, Toll-like receptor signaling pathway, IL-17 signaling pathway, Coronavirus disease, TNF signaling pathway and HIF-1 signaling pathway." (PMID 35935817, 2022). "They concluded that COVID-19-induced organ impairment is mostly facilitated by cytokine storms and that strategies to diminish or eradicate inflammatory cytokines would be effective in avoiding cytokine-induced organ injury, aiming to reduce IL1, IL6, TNF-α, and INF-γ levels." (PMID 35891270, 2022). "Regardless of the unchanged values of BDNF in different phases of COVID-19, we found a positive correlation between BDNF and MMP-9, MMP-8, and VEGF A, as well as a strong negative correlation of BDNF with IL-10 and cytokines ratios IL-10/IL-1, IL-10/IL-6, IL-10/IL-17, and IL-10/TNF-α." (PMID 36438922, 2022). "In the current study, any genotype associated with IL6 rs1800796, IL-10 rs1800896, TNF -α rs1800629, and IFITM3 rs12252 SNPs was significantly different between COVID-19 survivors with and without post-COVID pain, and, therefore, also with different pain phenotype features." (PMID 36233516, 2022).
COVID-19 (continued). "Moreover, patients with COVID-19 had significantly less central and effector memory CD4 T-cell subsets capable of IFNγ and TNFα co-expression in response to a polyclonal in vitro stimulation with PMA/Ionomycin mixture in comparison with the controls and COVID-19 convalescents." (PMID 35632823, 2022). "Moreover, IFNγ was not increased in patients with COVID-19 whereas TNFα levels were lower in COVID-19 patients than in patients with sepsis and CAR-T cell-induced CRS." (PMID 36158866, 2022). "The earliest reports of COVID-19 clarified that IL-1β, IL-6, TNFα, and CCL3 in the peripheral blood of patients with severe COVID-19 pneumonia were significantly higher than those of non-severe patients, and this cytokine storm is an important factor contributing to death from COVID-19." (PMID 35120332, 2022). "Moreover, COVID-19 patients have an enhanced level of chemokines and cytokines, such as interleukin-1 receptor antagonist (IL-1RA), IL-2, IL-6, IL-7, IL-8, IL-9, IL-10, IFN-γ, TNF-α, and the granulocyte-macrophage colony-stimulating factor." (PMID 36092161, 2022). "Despite the underlying causes of COVID-19 and regardless of the patient’s course of disease, MAIT cells were highly activated and produced large amounts of proinflammatory cytokines such as IL-17A and TNF-a." (PMID 36034704, 2022). "Indeed, an increase in cytokines such as TNF-α, MCP-1, IL-6, IL-1β, and IL-10 was shown in the rat ARDS model induced by LPS administration, which corresponds to the cytokine profile of patients with a severe form of COVID-19." (PMID 36290634, 2022). "Molecularly, synergism of TNF and IFN-γ engages the janus kinase (JAK)-STAT1 axis to induce IRF1 expression and nitric oxide (NO) production, which activates PANoptosis, underscoring the importance of these molecules in the pathology of COVID-19 and other cytokine storm syndromes." (PMID 36419185, 2022). "Anti-TNF users who did not have COVID-19 stopped taking the treatment for an average of 3 months (min 2–max 4 months) starting from March 2020, and the patients who had COVID-19 (p = 0.102) stopped taking the treatment for 1.5 months (min 1–max 2 months)." (PMID 36161620, 2022). "If ADAM17 expression is not downregulated by SIRT1, TNF-α and IL-6 are released, resulting in an uncontrolled hyperinflammatory response as may happen with COVID-19." (PMID 35458574, 2022). "Importantly, patients with severe COVID-19 show conspicuous increases in cytokines, including interleukin (IL)-6, monocyte chemoattractant protein (MCP)-1, IL-8, tumor necrosis factor (TNF)-α, IL-1, IL-18, and IL-17, with characteristics of the cytokine storm (CS)." (PMID 36147356, 2022). "Furthermore, IL-2, IL-7, IL-10, G-CSF, IP-10, MIP-1α and1β, and TNF-α were higher in ICU COVID-19 patients than non-ICU patients." (PMID 35401519, 2022). "That Virofree was able to decrease TNF-α secretion amount, fibrosis-related protein expression in vitro, and improve physiological indexes of ARDS rats in the preliminary in vivo, and results suggest that Virofree is a potential anti-COVID-19 and anti-fibrosis treatment." (PMID 35860023, 2022). "Therefore, the magnitude of the multifunctional T cell response gradually decreased in COVID-19 patients after two years of recovery, and the IFN-γ+TNF-α+ multifunctional SARS-CoV-2-specific mCD4+ T cell response could be activated post SARS-CoV-2 vaccination." (PMID 36494338, 2022). "Furthermore, a clear clustering of cytokines (IL-6, TNF-α, IFN-γ, IFN-α, SDF-1α, MIP-1α, MIP-1β, G-CSF, IL-10, CX3CL1 and IL-4) was observed in a PCA for critically ill COVID-19 patients during the first wave who presented a bacterial superinfection during their stay at the ICU." (PMID 35007290, 2022). "In addition to IL-6, the serum levels of IL-2R, IL-10, IL-1β, IL-4, IL-8, IL-17 and TNF-α were also elevated in both severe and non-surviving COVID-19 patients." (PMID 35237162, 2022).
COVID-19 (continued). "Moreover, at day 7, TNF and LPS-primed neutrophils produced significantly fewer ROS in superinfected than non-superinfected COVID-19 patients." (PMID 35637483, 2022). "A recent study showed that among the eight cytokines tested, TNF-α in combination with IFN-γ strongly induced inflammatory cell death, and administration of this cytokine combination to mice resulted in lethal cytokine shock which resembles COVID-19 related tissue damage and inflammation." (PMID 36034662, 2022). "Kaempferol might regulate inflammation, oxidative stress, immunity, virus infection, cell growth process and metabolism through targeting EGFR, IL-17, TNF, HIF-1, PI3K/AKT and Toll-like receptor signaling pathways to perform anti-COVID-19/PF co-occurrence effect." (PMID 35754492, 2022). "We found immune response related pathways (TGF-β, IL2-STAT5, IL6-JAK-STAT3, and TNFα signaling, Complement system activation, and Inflammatory response pathway) to be upregulated in the classical monocyte, NK cells, activated CD4+ T cells and CD4+ central memory T cells in active COVID-19 patients." (PMID 36532041, 2022). "The fact that the N-specific antibodies in children, but not adults, correlated with anti-N CD8+TNF-α+ memory T cells may evidence functional mechanisms of protection that have not been characterized for COVID-19." (PMID 36405692, 2022). "In this study, the top 11 hub genes pathways of COVID-19, RA, and pyroptosis were enriched in the Network map of the SARS-CoV-2 signaling pathway, Activation of the NLRP3 inflammasome by SARS-CoV-2, IL, NF-κB, TNF signaling pathway and regulation of cytokine-mediated signaling pathway." (PMID 36532040, 2022). "These indicated that FCGR3A, TNF, and CCL3 might be the key genes of COVID-19-related CU." (PMID 36531995, 2022). "The mechanism of the nervous system manifestations of COVID-19 may be that SARS-CoV-2-related cytokines such as IL-1b, IL-17, IL-6, and TNF alter the permeability of the blood-brain barrier, which makes SARS-CoV-2 can reach the brain and recognize ACE2 directly affects brain cells." (PMID 35774397, 2022). "Anti-TNF therapies, ustekinumab, and vedolizumab should be delayed for at least 2 weeks to monitor for symptom resolution but can be re-started once symptoms resolve, convalescent COVID-19 titers develop, or sequential viral testing is negative." (PMID 35496814, 2022). "The pathogenesis of COVID-19 is related to virus replication and infection, followed by inflammatory responses, which manifest as a cytokine storm in a severe course of illness that is characterized by elevated levels of IL1-β, IL-6, IL-8, ferritin and tumour-necrosis factor alpha (TNF-α)." (PMID 35997950, 2022). "To assess the general landscape of immune perturbation in different clinical settings of COVID-19, we contemporary measured the concentration in peripheral blood of six cytokines involved in the inflammation orchestrating: IL-6, IL-1β, IL-17A, TGF-β, TNF-α and IFN-γ." (PMID 35508575, 2022). "Therefore, it is likely that ORF3a-induced IL-6 and TNF-α production through NF-κB, TLR3 or TLR4 could all contribute to the severity of COVID-19." (PMID 35356515, 2022). "Compared to the healthy controls, patients with COVID-19 had significantly higher circulating concentrations of 19 inflammatory mediators, namely interleukins 1α, 2, 6, 7, 8, 10 and 15, CRP, SAA, ICAM-1, VCAM-1, CXCL10, CCL3, CCL26, IFN-γ, TNF-α, bFGF, PlGF and Flt-1 (P < 0.05)." (PMID 35958594, 2022). "In summary, the present findings provide further support for using SDC-1 alone or combined with other markers such as IL-6, TNF-α, CRP, PCT, and D-dimer as possible indicators for predicting severity and could be a valuable approach for monitoring the disease activity of COVID-19." (PMID 36556051, 2022).
COVID-19 (continued). "The host immune response of COVID-19 presents a signature called “the global immune signature” of SARS-CoV-2 infection, which consists of elevated serum cytokines (particularly IL-1β, IL-6 and TNF-α), impaired IFN responses, and peripheral lymphopenia as markers of severe disease." (PMID 35982454, 2022). "Thus, although the effect of one cytokine does not trigger COVID-19 complications, the TNF axis demands significant attention." (PMID 35631442, 2022). "Moreover, classical monocytes from severe COVID-19 patients displayed a type I IFN response together with the TNF/IL-1β-mediated inflammation, being absent in mild COVID-19 patients." (PMID 35663932, 2022). "In addition, only one patient treated with non-anti-TNFα had a marked increase in antibody titers, to 22,900 U/mL, at 20–28 weeks after the second vaccination without COVID-19 symptoms." (PMID 36298483, 2022). "Patients with inflammatory bowel disease (IBD) treated with anti-tumor-necrosis factor-alpha (TNFα) exhibited lower serologic responses one-month following the second dose of the COVID-19 BNT162b2 vaccine compared to those not treated with anti-TNFα (non-anti-TNFα) or to healthy controls (HCs)." (PMID 35893835, 2022). "Furthermore, there have been many case reports of patients using TNF inhibitors as treatment for COVID-19, demonstrating no respiratory complications or death." (PMID 35223745, 2022). "Given that about a half of patients enrolled in the cohort were on biologics and the number of patients used corticosteroids was low, the use of anti-TNFα antibodies may contribute to the lower rate of severe COVID-19, with no death cases." (PMID 35089397, 2022). "To explore whether the leucocyte response is limited by COVID-19, we stimulated cells with LPS or PMA/Ion, and a clear proinflammatory response with cytokines such as TNF-α, CCL3, CCL4, IL-17a, CCL23 and CXCL8 was detected in the supernatant, indicating that leucocytes are not anergic." (PMID 35901034, 2022). "There is little evidence on whether or not anti-TNF-mediated inhibition of the humoral response impacts the gut and COVID-19-induced GI damage." (PMID 36297092, 2022). "In a cohort of 43 COVID-19 patients and 25 healthy controls, circulating MAIT cells displayed reduced frequency and an activated phenotype in individuals with COVID-19, regardless of disease severity, as characterised by high expression of IL-17A, TNFα, CD38, CD69 and HLA-DR." (PMID 34050887, 2022). "Furthermore, we evaluated the expression of the most important inflammatory cytokines/chemokines commonly observed in COVID-19 patients, and we found that FBA was able to reduce the expression of IL-15, MCP-1 and TNF-α in human enterocytes exposed to WT SARS-CoV-2." (PMID 35164139, 2022). "The second phase, which is much more crucial in COVID-19 because it is an intracellular viral infection, results in the secretion of a variety of cytokines into the bloodstream by T cells and macrophages, of which IL1-β, IL-2, IL-8, IL-10, IL-6, IL-12, IFN-γ, and TNF-α are the best known." (PMID 35874678, 2022). "Indeed, in the most severe cases of COVID-19, there is an over-expression of certain cytokines, such as IFN-gamma, TNF-alpha and IL-6, with strong pro-inflammatory action: these molecules are able to activate also the coagulative cascade with the risk of disseminated intravascular coagulation." (PMID 35807096, 2022). "To obtain a complete picture of the adaptive immune response to anti–COVID-19 vaccination, we evaluated the antigen-specific CD4+ T cell response to SARS-CoV-2 spike protein peptides, monitoring CD154 expression and the production of IL-2, IFN-γ, and TNF-α upon in vitro stimulation." (PMID 35139036, 2022). "In addition, the plasma concentrations of both IL-26 and IL-8 displayed a negative correlation with the mean corpuscular hemoglobin (MCH) in whole blood from the COVID-19 group, while IL-6 and TNFα failed to correlate with MCH in this way." (PMID 36466824, 2022).